DKK1 (dickkopf Wnt signaling pathway inhibitor 1)
Diseases named in the same sentence as DKK1 in open-access papers (continued):
Sharing a sentence is not in itself a finding about the gene and the disease.
tumor (continued). "Another study demonstrated that DKK1 overexpression influences the immune cell population with anti-tumor antibody effects within the TME by reducing CD45+leukocyte infiltration levels and decreasing the abundance of natural killer cells (NKs) and CD8+T cells." (PMID 38376441, 2024). "While bone-derived DKK1 contributes to the systemic elevation of DKK1 in tumor-bearing mice, CAFs represent the primary source of DKK1 at the tumor site." (PMID 38659818, 2024). "Positive Dkk1 staining, on the other hand, was found in the vast majority (136/145) of pre-treated tumours, including 42 cases with strong staining." (PMID 38254908, 2024). "To further investigate the role of DKK1 during tumor dissemination, we injected the firefly luciferase-conjugated PyMT-BO1 cell line into albino C57BL/6 mice either intracardiacally (i.e.)or in the tibias (i.t.), followed by treatment with mDKN01." (PMID 38659818, 2024). "Annotating all cell subsets according to DKK1 expression, DKK1 were highly enriched in tumor cells subsets, and the violin plot demonstrated the same result." (PMID 39107271, 2024). "QRT-PCR showed that the expression of FAM83 and DKK1 was significantly upregulated in tumor samples, while SPINK7 was downregulated." (PMID 38518012, 2024). "IHC staining for CD31 showed that OTTs induced a large amount of vascular endothelium relative to STTs, in which the deletion of DKK1-SE reduced endothelial generation, consistent with the results of tumor surface generated blood sinuses." (PMID 39107271, 2024). "In this study, we found that Dkk1 expression in NACT-treated BC tumours was less frequent than in untreated tumours." (PMID 38254908, 2024). "Following NACT, the frequency of positive Dkk1 staining, the frequency of strong staining intensity, and the percentage of stained tumour cells >80% were significantly reduced by 37% (3% vs. 40%), 34% (6% vs. 40%), and 22% (59% vs. 81%), respectively." (PMID 38254908, 2024). "The results showed that the methylation levels of FAM83E, CD79A, and SPINK7 were reduced in tumor tissues with poor clinical staging, while DKK1 was elevated in tumor tissues." (PMID 38518012, 2024). "DKK1 expression was remarkably higher in HNSCC tissues than in healthy tissues, and was shown to be associated with tumor stage, grade, lymph node metastasis, histology, and a dismal clinical prognosis in HNSCC." (PMID 38376441, 2024). "Bone and CAF-derived DKK1 contribute to systemic and local increases in DKK1 levels during tumor progression." (PMID 38659818, 2024). "The hnRNPA2B1 was validated to interact with DKK1 mRNA and repressed its expression, which led to activation of the Wnt/β-catenin pathway and tumor growth." (PMID 38481876, 2024). "In this study, immunostaining for DKK1 using clinical specimens showed that staining of the tumor stroma gradually decreased with progressive malignancy, while staining of tumor adenoducts increased." (PMID 38334454, 2024). "Next, we administered the DKK1-neutralizing monoclonal antibody mDKN01 (10mg/kg), every other day following tumor inoculation and found a significant reduction in primary tumor growth compared to isotype control (IgG)." (PMID 38659818, 2024). "Based on the expression of DKK1 in aSMA+ cells in the tumor microenvironment, next, we crossed Dkk1fl/fl mice with the inducible aSMA CreERT2 line (referred to as aSMA-Dkk1cKO)." (PMID 38659818, 2024). "Correlations between DKK1-expression levels and tumor lymphocyte infiltration in HNSCC, as determined using the TISIDB database." (PMID 38376441, 2024). "We now find that local production of DKK1 at tumor site limits tumor immune infiltration, while DKK1 neutralization or its deletion in CAFs reverses these effects." (PMID 38659818, 2024). "Overall, the effect of DKK1 on tumor is controversial and appears to depend on several factors, such as the genetic background of the tumor entity and the tumor microenvironment." (PMID 39107271, 2024).
tumor (continued). "By intersecting these tumor marker genes with the top 50 DEGs of the immune exclusion tumor area, we pinpointed DKK1 as meeting the criteria while exhibiting the highest expression level." (PMID 39505867, 2024). "IHC staining showed that DKK1 expression was higher in tumor tissues compared to para-tumor tissues, with intense staining occurring in 66.6% of cases." (PMID 39107271, 2024). "Cox proportional hazard model of DKK1 and six tumor-infiltrating immune cell types in HNSCC, as determined using the TIMER database." (PMID 38376441, 2024). "To determine the role of bone versus CAF-derived DKK1 during tumor progression, we generated mouse models with targeted deletion of DKK1 in osteoblasts and fibroblasts." (PMID 38659818, 2024). "We find DKK1 to be highly expressed in osteolineage cells and that deletion of bone-derived DKK1 exerts profound anti-tumor effects." (PMID 38659818, 2024). "Conversely, DKK1+ tumor cells were observed to accumulate within the tumor area in immune exclusion samples, particularly at the tumor boundary." (PMID 39505867, 2024). "Meanwhile, DKK1 expression was positively correlated with the degree of differentiation of PDAC tumor." (PMID 39107271, 2024). "By directly targeting several Wnt/β‐catenin antagonists including AXIN1, GSK3β and DKK1, miR‐31 promotes the Wnt signalling pathway and tumour development within mammary and small intestine." (PMID 38797942, 2024). "The Wnt-signaling inhibitor and immune activation mediator, Dickkopf-1 (DKK1), has a strong correlation with tumor growth, tumor microenvironment, and, consequently, disease prognosis." (PMID 38376441, 2024). "Despite the low numbers of DKK1 positive cells, we found that the fraction of DKK1 positive tumor cells was significantly higher in pre-treatment samples compared to paired on-treatment samples (p=0.028, student t-test)." (PMID 39417106, 2024). "The impact of DKK1-SE deletion on PDAC tumor progression was explored using an in vivo mouse xenograft model, employing subcutaneous transplantation tumors (STTs) and orthotopic transplantation tumors (OTTs) in nude mice." (PMID 39107271, 2024). "We compared the membranous expression of β-catenin, cadherins and Wnt antagonist Dkk1 in tumour tissue as well as expression of hormone receptors (ER, PR and AR) against nuclear expression of β-catenin." (PMID 36969079, 2023). "Clinical evaluations across a spectrum of malignancies have detected amplified concentrations of this Wnt antagonist, Dickkopf-1(DKK1), within patient sera and neoplasms, frequently serving as harbingers of an unfavorable prognosis." (PMID 37796226, 2023). "In this study, we found that DKK1 changes the tumour microenvironment by altering immune cells that normally act against tumours." (PMID 35924447, 2023). "Generally, DKK1 participates in embryonic development but in cancer, it regulates tumour progression as it is a well‐known inhibitor of Wnt signalling pathway." (PMID 37277696, 2023). "These genes demonstrated an overall increase when DKK1 is overexpressed in our models compared to control tumours." (PMID 35924447, 2023). "Here, we report that DKK-1 has both autocrine and paracrine effects in the bone metastasis milieu, increasing tumor growth and decreasing the osteoblastic activity of PCa." (PMID 38067123, 2023). "DKK1‐driven changes to the tumour immune microenvironment were characterized by immunostaining and gene expression analysis." (PMID 35924447, 2023). "DKK1 was originally considered as a tumor suppressor as its expression level is reduced in gastrointestinal tumors and frequently silenced in cancer cells." (PMID 37086261, 2023). "On average 2.07% of cells were FOXP3 positive when DKK1 was highly expressed (n = 130), compared to 0.933% in control tumours (n = 57)." (PMID 35924447, 2023).
tumor (continued). "Its involvement in T-cell differentiation and fostering tumor subterfuge from immune scrutiny, primarily through the proliferation of MDSCs, has thrust DKK1 into the spotlight as a prospective linchpin in cancer immunotherapy." (PMID 37796226, 2023). "Third, SOR combined with DKK1 inhibitor also inhibited tumor progression by regulating apoptosis and cell cycle progression." (PMID 38012711, 2023). "We also detected the levels of the main proteins involved in tumor progression, DKK1 and SFRP1, by ELISA and cell senescence by β-galactosidase tests." (PMID 37374009, 2023). "In DKK1‐overexpressing Nicd/Akt‐driven iCCA we found an increase in the proportion of F4/80‐positive cells from 10.5% in control tumours (n = 832), to 15.58% in tumours that overexpressed DKK1 (n = 401) (p < .0001)." (PMID 35924447, 2023). "DKK1 can affect different kinds of cell populations in the GC TME, including tumor-associated macrophages and T cells." (PMID 37835450, 2023). "The interaction between DKK1 and cytoskeleton-associated protein 4 (CKAP4) offers a window into a deeper understanding of tumor biology and the development of new therapeutic strategies." (PMID 37835450, 2023). "Livers were excised from mice bearing either Nicd/Akt or Nicd/Akt/DKK1 expressing tumours and contained numerous iCCAs." (PMID 35924447, 2023). "Having defined how DKK1 modulates this system, we demonstrate that therapeutic targeting of DKK1 can drastically reduce tumour size and number in both hydrodynamic and damage‐induced mouse models of iCCA." (PMID 35924447, 2023). "TCGA datasets revealed significantly higher mRNA expression levels of DKK1 in patients with HCC (n = 373) than in those non-tumor tissues (n = 50) (P < 0.001)." (PMID 38012711, 2023). "Compared with normal tissues, only SLURP1 was downregulated in tumor tissues, while the expression levels of DKK1, GAST, IGHM, IL12RB2, STC2, and TNFRSF4 were upregulated in tumor tissues." (PMID 39282247, 2023). "By using genetically tractable mouse models of iCCA to understand the effect of DKK1 overexpression on the tumour immune microenvironment, we have shown that DKK1 is sufficient to drive profound immune changes within tumours." (PMID 35924447, 2023). "DKK1 is a member of the dickkopf family, which can inhibit Wnt signaling and regulate immune cells in the tumor microenvironment." (PMID 36732762, 2023). "First, DKK1 plays different roles in tumor progression in each tumor type, and the role of its dysregulation in human tumors remains controversial." (PMID 38012711, 2023). "Compared with the gastric benign group and healthy group, higher serum DKK1 protein levels were observed in GC patients." (PMID 37835450, 2023). "Expression of Dkk1 was also found to be higher for tumours with nuclear expression of β-catenin (Me [H-score] = 115) than for tumours without nuclear β-catenin expression (Me [H-score] = 102), U = 270.5, p < 0.05." (PMID 36969079, 2023). "The hypomethylation level in specific regions of the DKK1 gene is a protective factor for survival, and research has shown that DKK1 promotes tumor immune evasion and impedes anti-PD-1 treatment by inducing immunosuppressive macrophages in GC." (PMID 37260411, 2023). "The specific effects of Dkk-1 activity on tumor physiology are therefore unpredictable with examples of Dkk-1 serving as either a driver or suppressor of malignancy." (PMID 37007131, 2023). "We have shown that uncoupling DKK1 from its immune regulatory network by treatment with mDKN‐01 is effective at reducing tumour growth in multiple models of iCCA." (PMID 35924447, 2023). "Various in vivo GEMM mouse models and patient samples were utilized to assess the effects of tumour specific DKK1 overexpression in iCCA." (PMID 35924447, 2023). "Following Nicd/Akt/DKK1‐driven tumour initiation, mice were treated with an anti‐DKK1 neutralizing antibody (mDKN‐01) or vehicle control for 4 weeks." (PMID 35924447, 2023).
tumor (continued). "Evidence has shown that DKK1 is not only involved in osteogenesis but also plays a central role in promoting tumor bone metastasis." (PMID 36447119, 2023). "This analysis identified alterations in immune modulatory pathways as a key differential between DKK1 overexpressing and control tumours in this model." (PMID 35924447, 2023). "Dkk-1 is significantly more likely to serve as a tumor suppressor in tumors arising from ectoderm and endoderm while the converse is true for mesodermal tumors." (PMID 37007131, 2023). "Here, we show that DKK1 plays an immune regulatory role in vivo and inhibition reduces tumour growth." (PMID 35924447, 2023). "Downregulation of DKK1 via shRNA or mDKK1 combined with CDDP treatment significantly inhibited tumor growth when compared with that in the group treated with CDDP alone." (PMID 37835450, 2023). "DKK1 is a tumor suppressor in tumors arising from the ectoderm and endoderm and a promoter in mesodermal tumors." (PMID 37835450, 2023). "Having defined a relationship between DKK1 and Treg signatures in iCCA, we used a tissue microarray to assess the number of FOXP3+ cells in iCCA patient tissue and compared this to DKK1 protein levels from the same tumours." (PMID 35924447, 2023). "In conclusion, we found that DKK1 inhibition significantly enhanced the anti-tumor efficacy of SOR by inhibiting the PI3K/Akt and Wnt/β-catenin pathways and both pathways were connected via GSK3β in HCC." (PMID 38012711, 2023). "DKN-01, an anti-DKK-1 antibody, has been tested in a PCa mouse xenograft model with elevated DKK-1, showing significant inhibitory effects on tumor growth and angiogenesis in a natural killer cell-dependent manner." (PMID 38067123, 2023). "Our results indicate that DKK1 inhibition significantly enhances the anti-tumor efficacy of sorafenib by inhibiting the PI3K/Akt and Wnt/β-catenin pathways via regulation of GSK3β activity, suggesting a novel therapeutic strategy for HCC." (PMID 38012711, 2023). "DKK1 promotes tumour immune evasion in iCCA through the recruitment of immune suppressive macrophages." (PMID 35924447, 2023). "DKK-1 was found to exert cancer-promoting activity via its effects on tumor growth, metastasis, and angiogenesis." (PMID 38067123, 2023). "In the present study, we found that SOR combined with DKK1 inhibitor induced G0/G1 arrest in Huh7 cells and G2/M arrest in Hep3B cells and decreased tumor progression in xenograft mice generated using Hep3B cells." (PMID 38012711, 2023). "Accumulating evidence shows that dysregulation of DKK1 is involved in tumor development and progression." (PMID 37835450, 2023). "When DKK1 was overexpressed in this tumour model the proportion of FOXP3‐positive Treg was increased from an average of 5.3% (n = 64) in the vector control group up to 10.7% (n = 19) of cells (p < .001)." (PMID 35924447, 2023). "In this second model, the proportion of F4/80 cells was increased from an average of 25.94% (n = 62) in the control group up to 39.39% (n = 19) of cells when DKK1 was overexpressed in tumour cells (p = .0013)." (PMID 35924447, 2023). "DKK1 also drove a significant increase in chemokines and cytokines in these tumours including Ccl and Cxcl family members that are involved in the recruitment of various immune cell types." (PMID 35924447, 2023). "Using in vivo models of iCCA, we define the effects of high DKK1 expression on the tumour immune microenvironment and test the efficacy of DKK1 neutralization on tumour growth." (PMID 35924447, 2023). "The dickkopf WNT signaling pathway inhibitor 1 (DKK1) also exhibited tumor-promoting phenotype in LC." (PMID 36941988, 2023). "In human models of PCa (PC3), DKK1 inhibition blocked tumor growth through the activation of NK cells." (PMID 37366915, 2023).
tumor (continued). "Dickkopf-related protein 1 (DKK1) plays different roles in different cancers, and its aberrant expression is associated with tumor progression and poor prognosis." (PMID 37835450, 2023). "DKK1 is expressed in multiple tumor types, including BTC, but its impact and the clinical role of this pathway’s components are not completely understood." (PMID 35121803, 2022). "Dkk1 is a spatially and timely expressed antagonist of the Wnt/β-catenin pathway, which is a key player in tumor progression." (PMID 35337112, 2022). "Dickkopf-related protein 1 (DKK1) is an inhibitor of the Wnt/β-catenin signaling pathway and was previously considered a tumor suppressor." (PMID 35945448, 2022). "Although DKK1 has been reported to act as a tumor suppressor in various malignant tumors, opposing results regarding DKK1 expression and its role in cancer have been achieved recently." (PMID 36276289, 2022). "RBM47 inhibits tumor progression and metastasis by increasing the secretion of DKK1, which in turn inhibits tumor progression and metastasis." (PMID 36052258, 2022). "DKK1 is overexpressed in advanced prostate, correlating with poor clinical outcome, aggressive tumor growth, high Wnt signaling, and immune evasion (Section 2.3.2)." (PMID 35204808, 2022). "Other tumor suppressor genes that can be susceptible to methylation-induced silencing in RCC have been identified, such as Dickkopf1 (DKK1); WNT pathway regulatory genes; and secreted frizzed related protein (SFRP1)." (PMID 35159060, 2022). "DKN-01 is a humanized IgG4 antibody used to block the activity of DKK1, enhancing innate immune responses by the immunosuppressive effects of DKK1 in the tumor microenvironment." (PMID 35454818, 2022). "DKK-1 levels were similar between patients with bilobar tumor localization (n = 24) compared to single lobe localization (n = 73) (918 [range, 367–4515] pg/mL versus 930 [range, 199–2263] pg/mL; p = 0.196)." (PMID 36230730, 2022). "We evaluated the effects of anti-DKK-1 antibody treatment on tumor growth in vivo and of recombinant DKK-1 on cell proliferation, invasion, and angiogenesis in vitro." (PMID 35269944, 2022). "DkkMo reduced the expression of Dkk-1 and Aldh1a1, reduced expansion of OS tumours, preserved bone volume and architecture and stimulated tumour necrosis." (PMID 35277659, 2022). "In contrast, knocking out β-catenin in myeloid cells abolished the effect of anti-DKK-1 antibodies on tumor growth." (PMID 35892678, 2022). "DKK1 levels are higher in cervical cancer patients, resulting in lymphatic metastasis, and are related to tumor diameter." (PMID 35355709, 2022). "In conclusion, serum levels of DKK-1 are a sensitive biomarker for tumor size and for the efficacy of TACE in European patients with early or intermediate stage HCCs." (PMID 36230730, 2022). "Nevertheless, DKK1 acting as a tumor promoter, which played a critical role in the cancer progression." (PMID 36185284, 2022). "Knockdown of DKK1 enhanced CS-stimulated tumor invasion activity of MDA-MB-231 cells, suggesting that DKK1 sequesters CS to block ROR1/JNK signaling." (PMID 35712490, 2022). "Owing to its role in regulating tumor progression by inhibiting the classical Wnt pathway, most studies define Dkk1 as a biological marker with the potential to evaluate tumor diagnosis and prognosis." (PMID 36139498, 2022). "While Dkk-1 cannot be formally regarded as a proto-oncogene, the data herein suggest that Dkk-1 certainly appears to serve as a survival factor for tumours." (PMID 35277659, 2022). "Neutralizing anti-DKK-1 antibodies helps to attenuate MDSC accumulation in the tumor microenvironment and restore T-cell numbers." (PMID 35892678, 2022). "Our study demonstrates that both physiological (mice, primary murine cells, humans) and pathological (tumor cells) DKK1 activity fuels inflammatory cytokine production, which contributes to maladaptive inflammation in disease." (PMID 36539532, 2022).